AR (androgen receptor)
Diseases named in the same sentence as AR in open-access papers (continued):
Sharing a sentence is not in itself a finding about the gene and the disease.
breast carcinoma (continued). "Androgen receptor signaling is also emerging as a relevant pathway for breast cancer biology." (PMID 19695104, 2009). "Our results indicate a role for AR in this breast cancer subset." (PMID 19747394, 2009). "Analysis of Molecular Apocrine breast cancer implies that therapies targeting AR might be hampered if interactions with ErbB family members are not addressed." (PMID 19747394, 2009). "To pursue our goal we investigate a recently introduced subtype of ER- breast cancer that is hypothesized to result from AR signaling." (PMID 19747394, 2009). "However, the role of androgens and their receptors (AR) in breast cancer etiology and progression has been less profoundly studied and remains an unanswered question." (PMID 18507821, 2008). "Relationship between AR and MMPs and TIMPs expression in 111 breast carcinomas." (PMID 18507821, 2008). "Relationship between the expression of AR, MMPs and TIMPs by each cellular type in breast cancer." (PMID 18507821, 2008). "However, the expression level of both the AR gene and the AR protein in breast cancer was found to be positively correlated with axillary lymph node involvement." (PMID 18507821, 2008). "In addition, certain types of breast carcinoma, even high grade ones, are typically ER- and PR-negative, but AR-positive; a typical example of such tumors is the apocrine breast carcinoma." (PMID 18507821, 2008). "Because the ER and the androgen receptor belong to the steroid receptor superfamily, we examined whether these compounds affected ER expression and signaling in breast cancer cells." (PMID 17986353, 2007). "56% (19/34) mammary carcinoma and 20% (2/10) adenocarcinoma of ovary were positive for AR." (PMID 17020615, 2006). "AR expression in primary breast cancer has been observed in 34–100% of cases in several reports." (PMID 17020615, 2006). "AR expression in 56% (19/34) of the mammary carcinomas is in concordance with previous studies." (PMID 17020615, 2006). "Majority of breast carcinomas evaluated express AR as determined by IHC and biochemical studies." (PMID 17020615, 2006). "The hypothesis-generating study examined AR CAG length in 304 female BRCA1 mutation carriers (54% with breast cancer), and assessed breast cancer risk associated with CAG length as a continuous variable, and at a number of different cut-points." (PMID 15743497, 2005). "The AR exon 1 CAG repeat polymorphism does not appear to have an effect on breast cancer risk in BRCA1 or BRCA2 mutation carriers." (PMID 15743497, 2005). "Androgens regulate breast cancer cell proliferation via androgen receptor (AR)-mediated mechanisms." (PMID 9703283, 1998). "However, comparison of percentage positive cells using the amino- and carboxy-terminal AR antisera in individual breast cancer specimens revealed a subset of tumours with discordantly increased staining for the carboxy terminus." (PMID 8883401, 1996). "The expression of AR in primary breast cancers also suggests that the receptor may be involved in tumour responsiveness or in abnormal responses to endocrine therapies." (PMID 8883401, 1996). "Furthermore, this study aimed to validate the hypotheses of AR as a potential therapeutic target and a prognostic marker in breast cancer." (PMID 40870508, 2025). "Moreover, AR signaling has been shown to influence the metastatic potential of breast cancer cells." (PMID 40286049, 2025). "In addition to its potential role in regulating tumor growth, AR signaling may also affect the responsiveness of breast cancer cells to other hormonal therapies." (PMID 40286049, 2025). "AR expression has been found to vary across different subtypes of breast cancer, with some studies suggesting that AR-positive tumors may exhibit less aggressive characteristics and be associated with a better prognosis, while AR-negative tumors tend to be more aggressive and harder to treat." (PMID 40286049, 2025).
breast carcinoma (continued). "However, in ER-ve/HER2+ve breast cancer, AR could be oncogenic by regulating the levels of WNT7B and activating β-catenin, resulting in cell proliferation and tumor growth." (PMID 40940753, 2025). "Similarly, our identified link between miR-205 and the Androgen Receptor (AR) aligns with studies suggesting their expression levels could serve as predictive markers in breast cancer." (PMID 40924781, 2025). "Finally, AR expression inversely correlated with the production of M2 tumor-associated macrophage, CD3+, and CD8+ T cell infiltration in trastuzumab-treated HER 2-positive breast cancer patients, suggesting a stronger role of AR in immune cells within cancer metastasis and proliferation." (PMID 40406098, 2025). "For example, AR activation may influence the proliferation of mammary epithelial cells, which could have implications for both normal mammary gland development and the development of breast cancer." (PMID 40286049, 2025). "Similarly, in breast cancer, AR signaling may modulate DNA repair, particularly in response to DNA-damaging agents like DOX, which induces lethal double-strand breaks (DSBs) if unrepaired." (PMID 40940753, 2025). "Moreover preclinical findings showed that enzalutamide inhibits the growth of HER2 breast cancer cells, suggesting that the activity of AR inhibition might be anticipated in HER2 tumors, even independently of HER2 inhibition." (PMID 39814370, 2025). "Additionally, molecular analyses were only performed on the initial diagnostic biopsy, and no biopsy was conducted at disease recurrence, which could be a limitation, as HER2 and AR expression can evolve over time, as observed in breast cancer." (PMID 39814370, 2025). "Metastatic prostate adenocarcinoma may mimic primary breast carcinoma and can express ER and AR." (PMID 41510417, 2025). "The role of AR in breast cancer depends on whether ER is present and its activity." (PMID 40023399, 2025). "AR expression in canine mammary tumors has been correlated with well-differentiated tumor subtypes and favorable prognostic factors, suggesting that ARs may act as a tumor suppressor in these cases, a role similar to the one they play in ER-positive human breast cancer." (PMID 40286049, 2025). "However, early findings suggest that AR expression may play an essential role in both the pathogenesis and progression of mammary tumors in both species, potentially serving as a valuable biomarker and therapeutic target." (PMID 40286049, 2025). "Thus, a better understanding of ARs’ role in both human and canine mammary tumors could open up new avenues for targeted therapies aimed at modulating AR signaling to reduce metastasis and improve patient outcomes." (PMID 40286049, 2025). "Notably, various stromal cells also express ER or AR, which impacts breast cancer development." (PMID 39682229, 2024). "In this study, our aim is to determine whether the loss of AR expression in AA QNBCs results from miRNA regulation in QNBC patients and underlies disparity in QNBCs, improving the understanding of racial differences in breast cancer outcomes." (PMID 39769441, 2024). "Indeed, AR has a tumor suppressor role in ER+ breast cancers, which may be sustained in some contexts of ER- breast cancer." (PMID 38317241, 2024). "Thus, our data suggest that cannabinoids, by acting as AR antagonists with inverse agonist properties, might be a beneficial therapy in resistant scenarios, or might even impair the AR oncogenic role known for ER+ breast cancer cells treated with Exe." (PMID 39338407, 2024). "In addition, our datasets provide ample candidate AR interacting proteins in different contexts of breast cancer that may play a role in determining context-specific AR signaling activity." (PMID 38317241, 2024). "Whether AR serves a conserved function across all breast cancer subtypes is also currently unknown." (PMID 38317241, 2024). "AR is expressed in MDA-MB-231 breast cancer cells and could be a potential mechanism of action." (PMID 39768178, 2024).
breast carcinoma (continued). "This differential AR expression between luminal subtypes may partially explain the different 2D:4D ratio findings in our study and suggests a deeper, more complex interaction between prenatal hormone exposure and tumor biology in Luminal A breast cancer." (PMID 38877071, 2024). "Thus, AR activation suppressed ER signaling in ERα-positive breast cancer cells." (PMID 38339092, 2024). "Therefore, the combination therapy of HDACis and AR antagonists may be a possibility for treating breast cancer, especially LAR-type TNBC." (PMID 38594722, 2024). "Taken together, these results demonstrate that endosomal recycling inhibitors can modulate the levels of the nuclear receptors ER-α and AR, and that they may be effective at treating certain forms of breast cancer when used in combination with hormone receptor antagonists." (PMID 38228924, 2024). "Given the significant role of AR in breast cancer prognosis and treatment response, effective imaging to assess AR expression could greatly enhance patient selection for anti-androgen therapies, leading to more personalized and potentially more effective treatment strategies." (PMID 39768978, 2024). "In addition to ERα, AR is expressed in 70–90% of breast cancers." (PMID 39682229, 2024). "Therefore, the addition of an inhibitor targeting PI3K/Akt/mTOR to the combination including AR inhibitors may benefit some patients with metastatic ERα-positive/HER2-negative/AR-positive breast cancer." (PMID 38339092, 2024). "Importantly, there is functional crosstalk between the estrogen receptor and other steroid hormone receptors, such as the progesterone receptor (PR), glucocorticoid receptor (GR), and androgen receptor (AR) in breast cancer cells, as well as other cancer cell types, like endometrial." (PMID 37835383, 2023). "Furthermore, AR has emerged as a potential therapeutic target in breast cancer and its efficacy in AR+-TNBC (Stage I–III) patients is currently under evaluation, based on a protocol with enzalutamide (Enza) and paclitaxel (Px) before surgery (clinical trial NCT02689427)." (PMID 36766786, 2023). "Thus, ER positivity and AR positivity may reflect decreased immune response in the breast cancer microenvironment." (PMID 36721218, 2023). "Thus, the role of AR-initiated fission in breast cancer deserves further studies." (PMID 37686282, 2023). "Given the promising effects observed for the combination of Exe (10 μM) plus CBD (5 μM) on ERα and AR, and since we previously reported that Exe may exert its effects on breast cancer cells through a crosstalk between AR and ERα, this was further investigated for this combined treatment." (PMID 37173983, 2023). "However, the role of the AR in breast cancer is more complex." (PMID 37681860, 2023). "Therefore, in this retrospective research, we aimed to determine whether AR status was related to the ultrasound, clinicopathological features or prognosis of breast cancer and to demonstrate whether such a correlation existed in different molecular subtypes." (PMID 36929229, 2023). "Consequently, AR + breast cancer usually had lower histological grade and lower Ki-67 level." (PMID 36929229, 2023). "Therefore, it is clear that AR can be seen as a marker of a favorable outcome in breast cancer." (PMID 36929229, 2023). "There are many ways in which to classify breast cancer cell lines, although the most common strategy that has been used over the past few decades entails immunohistochemistry (IHC) methods to recognize different hormone receptors such as ER, PR, and androgen (AR)." (PMID 38137912, 2023). "Moreover, it has been suggested that AR acts as a tumor suppressor in the context of breast cancer." (PMID 37102205, 2023). "However, little is currently known about the expression of AR in breast cancer BrM." (PMID 37345085, 2023). "The prognostic relevance of AR may be different in different breast cancer subtypes." (PMID 37085500, 2023).
breast carcinoma (continued). "Furthermore, AR targeting strategies have been applied to clinical therapy in breast cancer." (PMID 37524746, 2023). "In addition, cyclin D1 is an AR target gene, downregulated by androgens in ER+ breast cancer cells." (PMID 37686282, 2023). "Finally, we also found that AR + breast cancer patients tend to have better prognosis." (PMID 36929229, 2023). "Moreover, it is important to remember the constant crosstalk between ERα and AR in ER+ breast cancer, which may explain the dependence of caspase-7 activity on AR levels." (PMID 37173983, 2023). "HR-/HER2 + breast cancer accounts for about 15–20% of all breast cancers, and our study showed that AR positive rate was 72.2% in this type of breast cancer, and the log-rank test showed that AR-positive patients had poor prognosis, which was partially consistent with some previous studies." (PMID 37099044, 2023). "Previous studies have shown that AR may be used as a prognostic predictor in breast cancers, but its role in neoadjuvant therapy and the relationship with prognosis of different molecular subtypes of breast cancer need to be further explored." (PMID 37099044, 2023). "Crabrolin-FR, crabrolin-AR, and crabrolin-PR with their increased number of charges, had lower anti-proliferative activities than crabrolin-TR, and the anti-proliferative activity of crabrolin-PR was relatively high (for example, for the human breast cancer (MCF-7) cells, its IC50 reached 12.29 μM)." (PMID 37833918, 2023). "Therefore, isolating CTCs from peripheral blood of breast cancer patients and detecting AR expression may be used to predict the occurrence of bone metastasis." (PMID 38041134, 2023). "AR has been considered a useful biomarker in BC, depending on the context of breast cancer subtypes." (PMID 36835056, 2023). "Thus, the AR should be a good prognostic factor in ERα+ve breast cancer." (PMID 36499670, 2022). "In addition to ERα, the androgen receptor (AR) is also expressed in 70–90% of breast carcinomas." (PMID 37435447, 2022). "Therefore, to search for new targets of pesticides in breast cells, we analyzed the expression of these miRNAs and of their predicted target genes in ER-, PR-, and AR-expressing breast cancer MCF-7 cells treated with various doses of p,p′-DDT, o,p′-DDT, or endosulfan." (PMID 35051067, 2022). "In ER-positive tumors, AR has an anti-proliferative effect by antagonizing ER, by binding to a subset of estrogen response elements (EREs); it can prevent the activation of target genes which mediate the stimulatory effects of 17-beta-estradiol on breast cancer cells." (PMID 35052843, 2022). "Furthermore, re-introduction of phosphor-mimic mutant AR-Y534D, but not wild-type AR reversed Kindlin-2 deficiency-induced inhibition of AR signaling and breast cancer progression." (PMID 35595729, 2022). "Thus, AR is a potential new therapeutic target in breast cancers." (PMID 37435447, 2022). "However, high AR expression may be associated with endocrine resistance, as patients with ER–positive breast cancer with high ratios of AR expression to estrogen receptor (ER) expression (AR/ER) have poorer disease–free survival (DFS)." (PMID 36556209, 2022). "Modulating AR activity could be a potential strategy for treating breast cancer." (PMID 36499670, 2022). "Furthermore, the AR may contribute to the growth of other malignancies, such as breast cancer, hepatocellular carcinoma and ovarian cancer, with ongoing clinical trials targeting the AR in patients bearing these cancers." (PMID 36499670, 2022). "In addition to TNBC, around 25% of breast cancer metastases express AR, whereas ER and PR levels are almost undetectable, but the role of AR in invasiveness is unknown." (PMID 36584207, 2022). "But they could effectively induce the degradation of AR in other AR+ breast cancer cell lines." (PMID 35680848, 2022).
breast carcinoma (continued). "Interestingly, some studies have shown that AR is also highly expressed in up to 70–90% of all breast cancer types, including as much as 30% of triple-negative breast cancers (TNBC) that are deficient in the expression of estrogen receptor α (ERα), progesterone receptor (PR) and HER2." (PMID 35013318, 2022). "However, the role of the AR in breast cancer is controversial." (PMID 36499670, 2022). "Indeed, increased anastrozole resistance was found in AR–overexpressing breast cancer patients." (PMID 36556209, 2022). "In contrast, for ERα-ve breast cancer, blocking the AR could confer better prognosis to patients." (PMID 36499670, 2022). "EGFR and BRCA1 may also affect the function of AR in breast cancers." (PMID 35053220, 2022). "Through in silico analysis, we identified 22 candidate genes that contained both ARE and ERE within the promoter region and confirmed that interleukin-8 (IL-8) had both functional ARE and ERE activity, suggesting that IL-8 could be regulated by both AR and ER in ER+ve breast cancer." (PMID 35054486, 2022). "Therefore, enzalutamide treatment, at best, appears to have little effect on the radiosensitivity of AR+/ER+ breast cancer cells, and at worst, enzalutamide may protect AR+/ER+ cells from RT-induced cell death." (PMID 35618789, 2022). "Therefore, AR leads to the better outcome of patients with ER + ve breast cancers." (PMID 35053220, 2022). "The breast cancer subtype phenotypically recognized as ER-negative was equipped with hormonally transcriptional genes in ER-positive cancers, which could be directed by endocrine strategy in an ER-independent but AR-dependent manner." (PMID 35847875, 2022). "However, in HER2-positive breast cancers, the relationship between AR and survival is unclear." (PMID 35207749, 2022). "However, the presence of AR expression itself may also predict a lower response rate to the standard cytotoxic chemotherapy similar to the endocrine sensitive breast cancer subtypes." (PMID 35711833, 2022). "Therefore, we speculated that overexpression of BQ would induce the activation of AR signaling in breast cancer cells." (PMID 35054486, 2022). "Interestingly, AR signaling in ER+ breast cancer is thought to be associated with favorable prognosis, and the reduction of HIPK3 and NCOA4 may negatively affect AR signaling and ER+ breast cancer prognosis." (PMID 35311114, 2022). "Therefore, addressing the upstream regulators of AR will be important in breast cancer." (PMID 35053220, 2022). "Thus, we hypothesize that FOXA1-driven AR expression in TNBC-basal SNAI1-mutant cells triggers a transcriptional program reminiscent of ER-mediated transcription in luminal breast cancer, whose exact mechanism awaits further investigation." (PMID 36171192, 2022). "Given the complexities of AR modulation in breast cancer subtypes and the unclear functional relationship of AR and ER in those subtypes, further studies are necessary to fully understand how pharmacological manipulation of AR function may be most effective in the clinical setting." (PMID 34680352, 2021). "Given the crosstalk of pathways triggered between different nuclear receptors, it may be possible that in the near future, breast cancer therapeutic decisions may require consideration of the expression of all four major steroid hormone receptors in breast cancer— ER, PR, AR and GR." (PMID 34638457, 2021). "Hence, AR-targeted therapies could be potential treatments for this most aggressive breast cancer subtype." (PMID 34392453, 2021). "In fact, AR-dependent signalling has been reported to exert either beneficial or deleterious effects on breast tissue, even if, under physiological conditions, its activation seems to protect against breast cancer development, at least in part for its ability to counteract ERα action." (PMID 35008851, 2021). "Also, AR is known to promote proliferation and migration of breast cancer." (PMID 33816302, 2021).